DROSHA (drosha ribonuclease III)
Diseases named in the same sentence as DROSHA in open-access papers (continued):
Sharing a sentence is not in itself a finding about the gene and the disease.
cancer (65 papers, 2007 to 2025). A tumor composed of atypical neoplastic, often pleomorphic cells that invade other tissues. "The per-cancer study showed that DROSHA mutation was impoverished in (a) lymph node metastatic in STAD tumors (p = 0.026) and COAD (p = 0.024), and (b) late (III/IV) stages in BLCA (p = 0.047) and UCEC (p = 0.036) cancers." (PMID 36672288, 2023). "In human cancers, mutations in DROSHA, DGCR8, and DICER1 are associated with several types of cancer." (PMID 37179717, 2023). "Methylation of one CpG site in the DROSHA promoter region was positively associated with cancer prevalence." (PMID 34885248, 2021). "Later, in similar types of childhood cancers, a similar pattern of somatic mutations was also identified in the corresponding residues (E1147, D1151) of the RIIIb in DROSHA." (PMID 33406242, 2021). "Our study generalized the status quo of the current studies on cancer-related polymorphisms in DROSHA and DGCR8 genes, supplying investigators with novel clues for identifying new biomarkers with cancer-forewarning function." (PMID 29654164, 2018). "First, all eligible articles were summarized to evaluate the correlation strength of each DROSHA SNP with the risk of overall cancer." (PMID 29654164, 2018). "We evaluated the correlation strength of the polymorphisms in DROSHA gene with cancer risk, based on the entire population." (PMID 29654164, 2018). "The overexpression of DROSHA caused by rs10719-C allele was elucidated to facilitate the proliferation and inhibit apoptosis of cancer cells, which was in-line with our meta-analysis findings." (PMID 29654164, 2018). "Previous studies have shown that several types of cancer are associated with alterations to miRNA machinery genes, such as DROSHA, DICER1, XPO5, and AGO2." (PMID 26147304, 2015). "The methylation level of DROSHA was inversely associated with time to cancer development." (PMID 34885248, 2021). "Therefore, it appears that any coding mutations in DROSHA or its cellular partners of the same pathway should be extensively studied in each individual case to predict the impact of the lesion on the cancer progression and consequent phenotype." (PMID 34572006, 2021). "Moreover, mutations in coding regions of DROSHA were also detected in several types of cancer, the majority of them acquired in the RNAase domains of the protein." (PMID 34572006, 2021). "And mounting studies have focussed on the correlations of DROSHA polymorphisms with cancer risk." (PMID 29654164, 2018). "Downregulation of Dicer or DROSHA expression is associated with an aggressive cancer phenotype." (PMID 28423353, 2017). "Moreover, correlations with cancer risk could also be observed in stratified analyses of DROSHA rs10719, rs6877842 SNPs and DGCR8 rs417309 SNP." (PMID 29654164, 2018). "Mutations in DROSHA or DGCR8 impair Microprocessor complex function, leading to a global reduction in miRNA levels in various cancers." (PMID 41154621, 2025). "These include mutations in DROSHA, DGCR8, and DICER1 in cancer, and recently identified AGO mutations in neurodevelopmental disorders." (PMID 40243428, 2025). "Genetic variants in miRNA processing genes, DROSHA and DICER, have been implicated in cancer susceptibility and progression in various populations." (PMID 39329954, 2024). "An increased rate in the proliferation of cancer cells of the lung adenocarcinoma was observed due to DROSHA knockdown." (PMID 38473318, 2024). "Genetic variants in the DROSHA (Gene ID: 29102) and DICER (Gene ID: 23405) have been investigated for their potential influence on miRNA processing and cancer susceptibility." (PMID 39329954, 2024). "Pooling the data from 45 articles, our results reveal the association of DROSHA (A > G; rs10719), DGCR8 (G > A; rs417309), RAN (A > G; rs3803012), and GEMIN3 (C > A; rs197414) with a 19–93% higher susceptibility to overall cancer." (PMID 36672288, 2023).
cancer (continued). "DROSHA (RNase III) is upregulated in a variety of cancers, although few studies have focused on its mechanism in promoting tumor development." (PMID 37007137, 2023). "Knock-down of DGCR8 results in, as observed upon DROSHA deplete on, a pronounced decrease in mature miRNA level affecting the expression of cancer-related genes." (PMID 36499151, 2022). "Impaired miRNA processing caused by the aberrant expression of miRNA biosynthesis genes DGCR8 and DROSHA can noticeably promote tumorigenesis, being correlated with pathophysiology of cancers." (PMID 36499151, 2022). "Altogether, for the first time in a non-cancer context, we report that high glucose downregulates DROSHA in an MDM2-dependent manner." (PMID 33801773, 2021). "Identifying TSS-miRNAs’ targets will be important in understanding the role this class of miRNA has in cancer where DROSHA is down-regulated and will facilitate the development of targeted therapies." (PMID 34914716, 2021). "The enhanced expression of these novel DROSHA isoforms in various cancer datasets suggest that alternative splicing is actively exploited to downregulate microprocessing in cancer." (PMID 34572454, 2021). "For example, mutations in or reduced expression of DROSHA and DICER1 in tumors associate with advanced tumor stage and poor clinical outcome in cancer patients." (PMID 34853298, 2021). "The role of RBPs in promoting cancer has been confirmed, and DROSHA, EXOSC8, HNRNPC, MRPS31, RPLP2, and SNRPB have also been reported to be related to the occurrence and development of a variety of tumors." (PMID 33981333, 2021). "The gain of DROSHA copy-number is found in more than 50% of advanced cervical squamous cell carcinomas, and its expression is upregulated in various types of cancers, which affect the global miRNA profile." (PMID 32138313, 2020). "By contrast, DROSHA expression has been also shown to be downregulated in many other types of cancers, suggesting its role as a tumor suppressor in different contexts." (PMID 32138313, 2020). "For example, HA binding to CD44 promotes Nanog association with DROSHA/p68 microprocessor complex resulting in the upregulation of miR-21 and downregulation of PDCD4 (a tumor suppressor protein) in cancer cells." (PMID 31293964, 2019). "Single nucleotide polymorphisms (SNPs) in miRNA biosynthesis genes DROSHA and DGCR8 were indicated to be correlated with cancer risk." (PMID 29654164, 2018). "In the present study, total seven SNPs in DROSHA and DGCR8 genes were comprehensively reviewed and analyzed to estimate their associations with the risk of overall cancer." (PMID 29654164, 2018). "Three of them (DROSHA rs10719, rs6877842, and DGCR8 rs417309) were revealed to be associated with risk of cancer in whole population or some particular subgroups." (PMID 29654164, 2018). "Current studies have indicated the role of DROSHA on the development of several sorts of cancers such as laryngeal, bladder, lung, and so on." (PMID 29654164, 2018). "In summary, we performed a systematic review on the association between DROSHA and DGCR8 polymorphisms and risk of cancer." (PMID 29654164, 2018). "Second, studies of DROSHA and DGCR8 polymorphisms on cancer predisposition field remain emerging, which resulted in limited number of the relevant investigations." (PMID 29654164, 2018). "We comprehensively reviewed and analyzed the effect of DROSHA and DGCR8 polymorphisms on cancer risk." (PMID 29654164, 2018). "Our aim is to explore the association of DROSHA and DGCR8 SNPs with cancer risk, supplying clues to researchers for screening novel cancer biomarkers." (PMID 29654164, 2018). "Previous studies have shown that microRNA machinery genes—such as DICER, DROSHA, XPO5, and RAN—are associated with cancer development." (PMID 27611467, 2016).
cancer (continued). "In this study, a meta-analysis was conducted to evaluate the association between SNPs in five genes (DROSHA, DGCR8, XPO5, RAN, and DICER1) involved in the canonical microRNA biogenesis pathway and human cancer risk." (PMID 27957388, 2016). "Analysis of primary cervical SCC samples and cell lines showed that the frequent copy number gains and overexpression of DROSHA led to an altered profile of miRNA expression, including the expression of many cancer-related miRNAs." (PMID 26156018, 2015). "Further analysis with the use of another oncogenomic tool, PPISURV, showed that the increased expression of DROSHA generally (across cancers/datasets) correlates with decreased survival." (PMID 26156018, 2015). "Recently, the E2F1-regulated ribonuclease DROSHA has been found to promote miR-630 biosynthesis in cisplatin-exposed cancer cells." (PMID 26263387, 2015). "Twenty-six carcinomas (87%) also exhibited significant over-expression of DICER (P=0.024) and 24 (80%) of the carcinomas presented a significantly increased DROSHA expression (P=0.03)." (PMID 23671264, 2013). "Using western blot and immunohistochemistry analyses, we confirmed the higher expression of TARBP2, DICER, and DROSHA at the protein level in carcinoma cases." (PMID 23671264, 2013). "Notwithstanding, overexpression or recruitment of DROSHA has been shown both to down- and up-regulate microRNAs in carcinoma samples." (PMID 20433755, 2010). "Regulation of miRNA expression at the level of DROSHA has previously been proposed for human cancer." (PMID 17922911, 2007). "DROSHA polymorphisms have been implicated in pediatric ALL and linked with cancer risk." (PMID 40699872, 2025). "The significance of mutations in DROSHA and DICER1 in cancer was extensively reviewed." (PMID 40243428, 2025). "Such dysregulation of RNaseIII type enzymes, nuclear DROSHA and cytoplasmic DICER, as well as components of the RISC complex, TARBP2 and AGO2, were reported in association with various types of cancers." (PMID 32660045, 2020). "Although the function of DROSHA is still controversial, either upregulation or downregulation of DROSHA expression alters the global miRNA expression profile, which is correlated with cancer progression and patient survival rate." (PMID 32138313, 2020). "It has been reported that the expression level of miR is regulated by DROSHA in human cancer." (PMID 31214494, 2019). "Thus far, accumulating studies have been concerned with the association between DROSHA and DGCR8 SNPs and the susceptibility to cancer." (PMID 29654164, 2018). "Analysis of associations between SNPs from DROSHA, DGCR8, XPO5, RAN, and DICER1 and cancer risk." (PMID 27957388, 2016). "Finally, somatic copy number changes of some of the analyzed genes including DROSHA correlate with survival of cancer patients." (PMID 26156018, 2015). "There were some studies describing the role of DROSHA in cancer." (PMID 26688807, 2015). "In conclusion, our results show that copy number variation may be an important mechanism of upregulation/downregulation of miRNAs in cancer and suggest an oncogenic role for DROSHA." (PMID 26156018, 2015). "Our results add to the complex picture of the role of DICER1 and DROSHA in cancer." (PMID 26156018, 2015). "Up to now, several groups have studied the role of DROSHA in cancer." (PMID 24312312, 2013). "We can hypothesize that even minor alterations in DROSHA activity might greatly affect the miRNA biogenesis and the generating content of miRNA, along with subsequent total dysregulation of protein expression during cancer progression." (PMID 34572006, 2021). "The encoding genes of the major DROSHA, DGCR8, and DICER1 components are frequently up-regulated in many solid tumors which modify the global miRNA expression profile and contribute to the main attributes of cancer progression, such as increased cell proliferation, migration and invasion." (PMID 31683635, 2019).
cancer (continued). "Together, variation of TARBP2, DICER, and DROSHA expression levels among different tumor types suggests that deregulation of miRNA-processing factors can be dependent on cellular context and imply their possible dual role as tumor suppressors or oncogenes in human cancers." (PMID 23671264, 2013). "Moreover, for carcinoma cases, we did not observe any significant association between DROSHA, DGCR8, DICER, TARBP2, or PRKRA mRNA levels and clinical–histopathological parameters such as gender, age, tumor size, or presence of metastasis (data not shown)." (PMID 23671264, 2013). "We found 10 and 16 original articles on DROSHA rs10719 and DICER rs3742330 and different types of cancers." (PMID 39329954, 2024). "We analyzed the mRNA expression levels of miRNA machinery components (DROSHA, DGCR8, XPO5, RAN, DICER, TARBP2, and AGO2) utilizing mRNA-Seq data from The Cancer Genome Atlas (TCGA) and The Genotype-Tissue Expression (GTEx) projects." (PMID 39404265, 2024). "Genes such as EGFR, PIK3CA, DROSHA, MDM4, and APC were located inside recurrently aberrant regions, while other known cancer-genes such as NF1, MET and mTOR were identified as cis-genes and located outside the most recurrently altered regions." (PMID 34625038, 2021). "All mentioned studies evaluated the expression of the DROSHA and DICER genes or their protein products in the tumour tissue or in cancer cell lines." (PMID 34885248, 2021). "The relative level of methylation of DROSHA was significantly lower and DICER significantly higher in cancer patients." (PMID 34885248, 2021). "The copy number variation of DICER1 and DROSHA correlates well with their expression and survival of NSCLC and other cancer patients." (PMID 26156018, 2015). "DROSHA and DGCR8 can be either upregulated or downregulated in cancers, often depending on the cancer type, which suggests the tissue- and cell-specificity of miRNAs and the diverse roles they play in cancer development." (PMID 41154621, 2025). "Studies have also discussed the downregulation of DROSHA and DICER in cancer." (PMID 38473318, 2024). "The microRNA (miRNA) expression levels are globally suppressed in human cancer compared to those in normal tissues, which are mostly contributed to genetic and epigenetic alterations in miRNA-processing machinery components such as DROSHA, DGCR8, XPO5, TARBP2, DICER, and AGO2 in human cancer." (PMID 30305728, 2019). "The combination of DROSHA up-regulation and DICER1 down-regulation can initiate accumulation of primary miRNA transcripts and incomplete miRNA maturation, and these can contribute to cancer progression." (PMID 31683635, 2019). "According to this theory, expression of DROSHA and DICER1 might play important roles in the function of specific miRs in human cancers in vivo." (PMID 31214494, 2019). "In conclusion, the DROSHA rs10719, rs6877842 SNPs, and DGCR8 rs417309 SNP play pivotal roles in cancerogenesis and may be potential biomarkers for cancer-forewarning." (PMID 29654164, 2018). "DROSHA could also significantly predict ACC cases (log-rank, P=0.038), although two carcinoma cases presenting metastasis at diagnosis were misclassified." (PMID 23671264, 2013). "Overall, it is becoming increasingly evident that DICER and DROSHA are essential for DDR activation and are involved in DNA repair (d'Adda di Fagagna, 2014; Francia, 2015), a function that might contribute to the prevention of cancer development." (PMID 33558311, 2021). "However, the findings were inconsistent and there was no systematic analysis for DROSHA and DGCR8 SNPs and cancer risk." (PMID 29654164, 2018). "Review of the Cancer Gene Census (COSMIC database) reveals no proto-oncogene in close proximity of either DROSHA or DICER1 that might drive their amplification." (PMID 26156018, 2015).
cancer (continued). "The knowledge obtained from this biogenesis study of miR-21 regulated by Nanog-DROSHA-p68 complexes may provide useful foundation for designing new drug target to downregulate miR-21 and increase tumor cell death and enhance chemosensitivity for the treatment of HA/CD44-mediated cancer." (PMID 31293964, 2019). "We eliminated 83 records after browsing the titles and abstracts (40 were functional studies; 12 were reviews or meta-analysis; 9 were not case–control studies; 52 were unrelated to DROSHA or DGCR8 SNPs; 8 were unrelated to cancer; 12 were not correlated with cancer risks)." (PMID 29654164, 2018). "Regardless of whether DROSHA and DICER1 are drivers of their amplifications, the amplifications of these two key miRNA biogenesis genes may increase their expression and, as a consequence, may contribute to the global destabilization of miRNA expression observed in many types of cancer." (PMID 26156018, 2015).